CASQ2 (calsequestrin 2)
Description:
Calsequestrin is a high-capacity, moderate affinity, calcium-binding protein and thus acts as an internal calcium store in muscle. Calcium ions are bound by clusters of acidic residues at the protein surface, especially at the interface between subunits. Can bind around 60 Ca(2+) ions. Regulates the release of lumenal Ca(2+) via the calcium release channel RYR2; this plays an important role in triggering muscle contraction. Plays a role in excitation-contraction coupling in the heart and in regulating the rate of heart beats.
Synonyms: PDIB2
Tractability: Small molecule: it has a binding pocket of medium quality. Antibody: UniProt predicts a signal peptide or a membrane-spanning region.
Gene: Protein-coding gene on chromosome 1 (115,698,038 to 115,837,921, reverse strand). Ensembl gene ENSG00000118729.
Subcellular location: Sarcoplasmic reticulum lumen
Pathways (Reactome):
Muscle contraction: Ion homeostasis
Transport of small molecules: Stimuli-sensing channels
Gene Ontology:
Molecular function: calcium ion binding; calcium ion sequestering activity; calcium-dependent protein binding; protein binding
Biological process: cardiac muscle contraction; cellular response to caffeine; intracellular calcium ion homeostasis; protein polymerization; regulation of cardiac muscle contraction by regulation of the release of sequestered calcium ion; regulation of cell communication by electrical coupling; regulation of heart rate; detection of calcium ion; negative regulation of potassium ion transport; Purkinje myocyte to ventricular cardiac muscle cell signaling; regulation of membrane repolarization; regulation of membrane repolarization during ventricular cardiac muscle cell action potential; regulation of release of sequestered calcium ion into cytosol by sarcoplasmic reticulum; striated muscle contraction; regulation of release of sequestered calcium ion into cytosol; sarcomere organization
Cellular component: cytoplasm; calcium channel complex; junctional sarcoplasmic reticulum membrane; sarcoplasmic reticulum; sarcoplasmic reticulum lumen; sarcoplasmic reticulum membrane; Z disc; junctional membrane complex
Genetic constraint (gnomAD): Loss-of-function variants: 30 observed, 30.78 expected, observed/expected ratio (o/e) 0.97, 90% interval 0.73 to 1.32. The upper end of that interval is the gene's LOEUF score, 1.32, which puts it in group 5 of 6, group 1 being the genes least tolerant of losing a copy. Missense variants: 385 observed, 401.82 expected, observed/expected ratio (o/e) 0.96, 90% interval 0.88 to 1.04. Synonymous variants: 139 observed, 149.44 expected, observed/expected ratio (o/e) 0.93, 90% interval 0.81 to 1.07.
Gene-disease validity (ClinGen):
ClinGen rates the evidence that CASQ2 causes each of these diseases.
catecholaminergic polymorphic ventricular tachycardia (autosomal recessive): Definitive. Catecholaminergic polymorphic ventricular tachycardia (CPVT) is a severe genetic arrhythmogenic disorder characterized by adrenergically induced ventricular tachycardia (VT) manifesting as syncope and sudden death.
catecholaminergic polymorphic ventricular tachycardia (autosomal dominant): Moderate.
hypertrophic cardiomyopathy (autosomal dominant): Disputed. A condition in which the myocardium is hypertrophied without an obvious cause.
Homologues: Orthologues: chimpanzee CASQ2 (99% identical), macaque CASQ2 (97% identical), rabbit CASQ2 (94% identical), dog CASQ2 (94% identical), guinea pig CASQ2 (92% identical), pig CASQ2 (92% identical), rat Casq2 (92% identical), mouse Casq2 (90% identical), zebrafish casq2 (69% identical), tropical clawed frog casq2 (69% identical), Caenorhabditis elegans csq-1 (30% identical). Paralogues in human: CASQ1 (62% identical).
Diseases named in the same sentence as CASQ2 in open-access papers:
CASQ2 is named in the same sentence as 49 diseases in open-access papers, as found by Europe PMC text mining. Sharing a sentence is not in itself a finding about the gene and the disease. The quoted sentences say what the papers report.
catecholaminergic polymorphic ventricular tachycardia (35 papers, 2012 to 2026). "Disruption of CASQ2 function is increasingly recognized as a driver of certain types of arrhythmias, notably catecholaminergic polymorphic ventricular tachycardia (CPVT) and heightened risk of sudden cardiac death." (PMID 41622389, 2026). "Catecholaminergic Polymorphic Ventricular Tachycardia (CPVT) (OMIM ID#611938) is typically caused by a compound heterozygous or homozygous variation in the CASQ2 gene." (PMID 39062601, 2024). "Mutations in CASQ2 cause fatal ventricular arrythmia, referred to as catecholaminergic polymorphic ventricular tachycardia 2 (CPVT2), and the C-terminal end of this gene, where the variant (E388G) we found is located, is known to be functionally important." (PMID 37180804, 2023). "Mutations in CASQ2 have been linked to the arrhythmia catecholaminergic polymorphic ventricular tachycardia (CPVT2) that occurs with acute emotional stress or exercise can result in sudden cardiac death (SCD)." (PMID 36672764, 2022). "In cardiac muscle, gain-of-function mutations in RYR2 and loss-of-function mutations in CASQ2 cause a similar phenotype, i.e. catecholaminergic polymorphic ventricular tachycardia (CPVT), which is caused by excessive SR Ca2+ leak." (PMID 36311237, 2022). "Homozygous calsequestrin 2 (CASQ2) point mutations leads to catecholaminergic polymorphic ventricular tachycardia: a common pathogenetic feature appears to be the drastic reduction of mutant CASQ2 in spite of normal transcription." (PMID 32902830, 2020). "Catecholaminergic polymorphic ventricular tachycardia (CPVT) is a stress-induced ventricular arrhythmia associated with cytoplasmic calcium leakage due to mutations in calsequestrin 2 (CASQ2), ryanodine receptor (RyR2), triadin, or calmodulin." (PMID 33329039, 2020). "CASQ2 gene variants associated with catecholaminergic polymorphic ventricular tachycardia (CPVT) in humans are positively correlated with a high degree of evolutionary conservation across all calsequestrin homologues." (PMID 33093545, 2020). "Biallelic variants of the CASQ2 are known to cause the autosomal recessive form of catecholaminergic polymorphic ventricular tachycardia (CPVT), an inherited disease that predisposes young individuals to syncope and sudden cardiac death." (PMID 31482657, 2019). "Catecholaminergic polymorphic ventricular tachycardia is caused by mutations in genes encoding ryanodine receptor type 2 (RyR2) and cardiac calsequestrin (CASQ2)." (PMID 30296944, 2018). "Catecholaminergic polymorphic ventricular tachycardia is a malignant inherited arrhythmia caused by mutations in the RyR2 and CASQ2 genes." (PMID 26153920, 2015). "Catecholaminergic polymorphic ventricular tachycardia is a familial cardiac arrhythmia that is related to RYR2 or CASQ2 gene mutation." (PMID 22557844, 2012). "It has been known that mutations in CASQ2 lead to catecholaminergic polymorphic ventricular tachycardia (CPVT), which may trigger cardiac arrest." (PMID 34912794, 2021). "This domain is essential for SR targeting and CASQ2 polymerization, with variants in this region linked to catecholaminergic polymorphic ventricular tachycardia (CPVT)." (PMID 39900885, 2025). "Loss-of-function variants in CASQ2 can result in catecholaminergic polymorphic ventricular tachycardia (CPVT), bradycardia, and atrial arrhythmias." (PMID 33868385, 2021). "Loss-of-function mutations of CASQ2 and RyR2 have been associated with catecholaminergic polymorphic ventricular tachycardia (CPVT), and CPVT patients often present with SAN bradycardia." (PMID 25863800, 2015). "The hereditary pro-arrhythmic condition catecholaminergic polymorphic ventricular tachycardia (CPVT), is associated with gene mutations involving ryanodine receptor type 2 (RYR2), calsequestrin (CASQ2), triadin (TRDN) or calmodulin (CALM1, CALM2 and CALM3)." (PMID 34643236, 2021).
catecholaminergic polymorphic ventricular tachycardia (continued). "It should be noted, that both catecholamine challenge and exhaustive exercise with ECG monitoring have shown that Casq2-/- mice display cardiovascular dysfunction in the form of catecholaminergic polymorphic ventricular tachycardia." (PMID 26859763, 2016). "Although CASQ2 has been associated with catecholaminergic polymorphic ventricular tachycardia, its role in breast cancer has not been reported before." (PMID 34743414, 2022). "The dual Na+ and cardiac Ca2+-release channel inhibitor, Flecainide (FLEC) is effective in patients with catecholaminergic polymorphic ventricular tachycardia (CPVT), a disease caused by mutations in cardiac Ca2+-release channels (RyR2), calsequestrin (Casq2), or calmodulin." (PMID 31456692, 2019). "Catecholaminergic polymorphic ventricular tachycardia (CPVT) is a relatively rare inherited arrhythmic disease that causes sudden cardiac death, and is caused by mutations in the cardiac ryanodine receptor (RyR2) or sarcoplasmic reticulum protein calsequestrin 2 gene (CASQ2)." (PMID 36540835, 2022). "Genetic gain of RyR2 or loss of calsequestrin function is associated with the pro-arrhythmic condition catecholaminergic polymorphic ventricular tachycardia (CPVT) experimentally recapitulated in murine hearts carrying genetically altered RyR2 or calsequestrin-2." (PMID 37122224, 2023). "In another study, the Calsequestrin 2 (CASQ2) gene was delivered in CASQ2-knockout and CASQ2R33Q/+ mice mediated by AAV9 as a delivery mean to rescue their phenotype of Catecholaminergic Polymorphic Ventricular Tachycardia, an aggressive form of arrhythmia during exercise." (PMID 31316392, 2019). "In our previous works, we have found similar changes (fragmentation of CRUs), i.e., reduction in size of RYR2 clusters, in mouse models lacking calsequestrin-2 (CASQ2) and carrying human mutations in CASQ2 linked to catecholaminergic polymorphic ventricular tachycardia." (PMID 34445071, 2021). "Although not discussed in this review, CASQ2 is closely related to human diseases, especially catecholaminergic polymorphic ventricular tachycardia (CPVT, an arrhythmogenic disorder characterized by physical or emotional stress-induced syncopal events and finally sudden cardiac death)." (PMID 33288873, 2020).
Arrhythmia (24 papers, 2012 to 2026). Any cardiac rhythm other than the normal sinus rhythm. "In a separate study, augmentation of CASQ2 expression in a model of RYR2-mediated CPVT1 significantly mitigated arrhythmia susceptibility." (PMID 40843724, 2025). "Based on simulation findings, these studies are unable to support the DADs being the mechanism of an arrhythmia in the heart having mutation in the protein of CASQ2 expressing genes under the rapid pacing seen during β-adrenergic stimulation." (PMID 36672764, 2022). "We used histologic analysis to relate the type of cells expressing Casq2 with arrhythmia susceptibility to catecholamine challenge or exercise." (PMID 34990403, 2022). "Reduction in CASQ2 levels and/or mutations of Casq2 can cause arrhythmogenic calcium release, leading to premature ventricular contractions and arrhythmia." (PMID 33931651, 2021). "In this study, we examined the effect of acute upregulation of SERCA2a on myocyte Ca cycling and arrhythmia susceptibility in the setting of hyperactive RyR2s using CASQ2 KO mice with doxycycline inducible overexpression of cardiac SERCA2a (KO-TG/DOX+)." (PMID 32260593, 2020). "CASQ2 plays an integral role in cardiac regulation, and its mutations have been associated with cardiac arrhythmia and sudden death." (PMID 33256812, 2020). "Both Casq2-/- mice and patients with CASQ2 mutations develop arrhythmias, catecholaminergic ventricular tachycardia, and can be diagnosed with exercise testing." (PMID 26859763, 2016). "This may be related to catecholamine-induced polymorphic ventricular tachycardia (CPVT) in which adrenergic stimulation can frequently cause lethal arrhythmias in mice with CASQ2 loss of function alterations." (PMID 23508205, 2013). "SCR, DAD, and TA are responsible for the onset of arrhythmias in various clinical settings including digitalis-induced arrhythmias, some forms of heart failure and catecholaminergic polymorphic VT (a genetic arrhythmia syndrome caused by mutations of the RyR and CASQ2 genes)." (PMID 23060805, 2012). "Since its discovery in CASQ2 KO mice, flecainide has become the standard of care for preventing arrhythmias in CPVT patients when betablockers are insufficient." (PMID 37775650, 2023). "Most of these variants were located in genes associated with inherited arrhythmias and arrhythmic cardiomyopathies, such as MYBPC3, KCNQ1, TTN, CASQ2, GPD1L, DPP6, HCN4 and NEXN." (PMID 36008935, 2022). "VM-Casq2–/– mice had significant ventricular arrhythmias, with similar arrhythmia burden as whole-heart Casq2–/– mice (P = 0.29)." (PMID 34990403, 2022). "When mice with the CASQ2-D307H knock in variant were injected with TRAM-34, electrocardiographic recordings showed reduced arrhythmias (and reduced severity of arrhythmias) at rest and during exercise." (PMID 33868385, 2021). "The major genes responsible for such inherited arrhythmias are RYR2 (encoding for RYR2), CASQ2 (encoding for calsequestrin-2), and CACNA1C (encoding for CaV1.2)." (PMID 31426283, 2019). "In the mouse, CASQ2 deletion causes a severe exercise- and/or catecholamine-induced arrhythmia phenotype consistent with patients lacking Casq2 expression." (PMID 37775650, 2023). "The arrhythmia rates in the complete VM KO group were essentially the same as for the whole-heart Casq2–/– model (P = 0.94), whereas the juxta-Purkinje group had significantly fewer ectopic beats and reduced arrhythmia burden compared with the whole-heart Casq2–/– group (P < 0.001)." (PMID 34990403, 2022). "To determine whether loss of Casq2 only in Purkinje cells is sufficient to induce a CPVT phenotype, we tested arrhythmia susceptibility in our selective Casq2–/– models." (PMID 34990403, 2022). "To test whether the ventricular cardiomyocytes are the cellular origin for CPVT, we examined arrhythmias in mice in which Casq2 was selectively knocked out in the VM but maintained in the Purkinje cells." (PMID 34990403, 2022).
Arrhythmia (continued). "Cardiomyocyte-specific knockout of CASQ2 increased prevalence of VT, whereas chemical ablation of the endocardium reduced arrhythmia burden, and it was suggested that subthreshold DADs in the endocardium could induce retrograde activation of Purkinje fibres and subsequently PVCs." (PMID 40612651, 2025). "Also, arrhythmias in iPSC-CM carrying RyR2-R420Q and CASQ2-D307H, evoked by isoproterenol, a synthetic catechol compound, or even sometimes pacing alone, were associated with an elevation in the resting level, probably resulting from a prominent diastolic intracellular Ca2+ rise." (PMID 35399287, 2022). "To explore the role of TCTP in the development of arrhythmias, we examined the effects of cardiomyocyte-specific TCTP overexpression in Casq2 KO mice, a mouse model of ventricular arrhythmia." (PMID 40181823, 2025). "To investigate the role of TCTP expression in the development of arrhythmias, we generated cardiomyocyte-specific TCTP-overexpressing mice with a Casq2 KO background (TCTPTG-Casq2 KO), a mouse model of ventricular arrhythmias." (PMID 40181823, 2025). "We found that VM-Casq2–/– mice have an arrhythmia burden equivalent to that of global Casq2–/– mice, whereas expression of Casq2 only in the Purkinje cells did not protect against catecholamine-induced VT." (PMID 34990403, 2022). "Our data showed that restoration of Casq2 at a median (nonzero) distance of 53.8 μm from the nearest Cntn2-positive (Purkinje) cells was sufficient to prevent arrhythmias, indicating that distal (epicardial) cardiomyocytes, despite lacking Casq2, are not the cellular trigger for CPVT." (PMID 34990403, 2022).
Ventricular arrhythmia (14 papers, 2019 to 2025). "Predisposition to ventricular arrhythmias after catecholaminergic stimulation is a hallmark of the CPVT model of CASQ2 KO mice." (PMID 32260593, 2020). "The class Ic anti-arrhythmic drug flecainide, commonly known as an inhibitor of membrane Na+ channels, has been shown to have clinical efficacy for preventing ventricular arrhythmias in CPVT patients carrying either Casq2 or RyR2 mutations." (PMID 31456692, 2019). "Both RYR2 and CASQ2 mutations cause spontaneous premature SR Ca releases in ventricular myocytes that facilitate the generation of delayed afterdepolarizations (DADs) and focal ventricular arrhythmias." (PMID 34990403, 2022). "However, while diastolic SR Ca2+ leak (Ca2+ spark frequency) was unaltered at basal levels, isoproterenol stimulation caused increased SR Ca2+ leak, making CASQ2-deficient mice more susceptible to stress-induced ventricular arrhythmias." (PMID 34558411, 2021). "Specifically, mutations in the RyR2 and CASQ2 genes lead to a leakage of Ca2+ from the SR in diastole, particularly under adrenergic stress (exercise, emotional stress), resulting in delayed after-depolarizations and therefore vulnerable to ventricular arrhythmias." (PMID 31380394, 2019). "By delivering wild-type CASQ2 to Casq2-knockout mice, they effectively abolished adrenergically induced ventricular arrhythmias, thereby providing proof-of-concept for gene therapy in autosomal recessive CPVT." (PMID 40843724, 2025). "Despite its bradycardic action, ivabradine was unable to prevent in vitro the occurrence of DADs and abnormal Ca2+ transients in the presence of isoproterenol as well as in vivo the ventricular arrhythmias in CASQ2-D307H KI mice." (PMID 32009964, 2019). "Indeed, moderate atrial overdrive pacing reduced ventricular arrhythmias during catecholamine stimulation in CASQ2-null mice and reduced DADs in isolated ventricular myocytes." (PMID 40612651, 2025). "Endocardial ablation prevents ventricular arrhythmia in Casq2–/– mouse hearts." (PMID 34990403, 2022). "Optical voltage mapping indicates focal origin of ventricular arrhythmias in Casq2–/– mouse hearts." (PMID 34990403, 2022). "We hypothesize that upregulation of SERCA2a in the CASQ2 KO ventricular myocytes would exacerbate aberrant diastolic Ca release by further facilitating SR Ca uptake, thus contributing to the exacerbated ventricular arrhythmias as observed in the DOX+ mice." (PMID 32260593, 2020). "Similarly, ivabradine was unable to prevent the aberrant Ca2+ transients found in SAN and to reduce the ventricular arrhythmias observed in the ECG from CASQ2-D307H KI mice." (PMID 32009964, 2019). "In vivo telemetric electrocardiograms (ECG) measurements showed that treatment with the SK4 channel blockers, TRAM-34 and clotrimazole, triggered sinus bradycardia and greatly reduced the ventricular arrhythmias of CASQ2-D307H KI and CASQ2 knockout mice at rest and following exercise." (PMID 32009964, 2019). "Thus, acute upregulation of SERCA2a exacerbated ventricular arrhythmias in the CASQ2 KO mice." (PMID 32260593, 2020). "To identify the origin of ventricular ectopy within the working VM, we first mapped ventricular activation of the epicardial surface of Casq2–/– hearts during sinus rhythm and during ISO-induced ventricular arrhythmias." (PMID 34990403, 2022). "When Casq2 was knocked out only in the Purkinje cells (PC-Casq2–/–), no ventricular arrhythmias were observed despite injection with both 3.0 mg/kg ISO and 60 mg/kg caffeine." (PMID 34990403, 2022). "In contrast, 9 out of 12 TRAM-34-treated (20 mg/kg) CASQ2-D307H KI mice exhibited normal sinus rhythm at rest, while following treadmill exercise, 4 out of 12 animals remained with normal sinus rhythm without significant ventricular arrhythmia." (PMID 32009964, 2019).